TWIST1 (twist family bHLH transcription factor 1)
Diseases named in the same sentence as TWIST1 in open-access papers (continued):
Sharing a sentence is not in itself a finding about the gene and the disease.
cancer (continued). "Controlling the expression of TWIST1 and other EMT mediator proteins might be an interesting and potential target in cancer therapeutics." (PMID 26023736, 2015). "It has not previously been determined if the downstream targets of Twist1 related to regulation of cell migration or proliferation in embryonic structures and cancer cells are shared or are cell-type specific." (PMID 25262113, 2014). "Furthermore, 3 out of 10 were epigenetically regulated by PRC2 in ES cells (TWIST1, ISL2 and SIM2), suggesting an important role of methylation events on these genes affecting cell differentiation processes and cancer." (PMID 23468990, 2013). "Twist1, which is a highly conserved transcription factor that belongs to the family of basic helix-loop-helix proteins, has been shown to be a major regulator of the epithelial-mesenchymal transition (EMT), and therefore promotes carcinoma metastasis." (PMID 22245869, 2012). "As regulators of invasiveness, TWIST1 and SNAI2 are potential targets for therapeutic modulation, a proposition further supported by their known functions to promote cell survival and treatment resistance in other cancer types." (PMID 20646316, 2010). "Together these studies demonstrated that TWIST1 enhances GBM invasion in concert with mesenchymal change not involving the canonical cadherin switch of carcinoma EMT." (PMID 20646316, 2010). "The expression of HAND2 (heart- and neural crest derivatives-expressed 2) and TWIST1 (twist family bHLH transcription factor 1) was significantly upregulated, while the expression of NKX2-5 (NK2 Homeobox 5) was significantly downregulated in MSCs compared to cancer cell lines." (PMID 39621192, 2025). "Interestingly, another EMT inducer Twist1 was shown to downregulate cell cycle checkpoints involved in genome stability and CIN-high PDOs were successfully classified using the transcriptomic EMT signature, as previously reported with CIN cancer cell lines." (PMID 40022181, 2025). "Therefore, despite the limitations, we assume that the results of our study on DNA methylation of apoptosis-associated genes suggest the possible involvement of five genes (SETDB1, TWIST1, HDAC1, SP1, and GRIA2) in the phenomenon of inverse comorbidity of neurodegenerative diseases and cancers." (PMID 40843670, 2025). "Increased matrix stiffness promotes the nuclear localization of the transcription factor Twist1 by decreasing the expression of its cytoplasmic binding partner, Ras-GTPase activating SH3 domain binding protein 2, thereby inducing invasion and metastasis of cancer." (PMID 40211368, 2025). "However, while TWIST1 has been observed to mediate chemoresistance across several cancer types, the authors did not see chemosensitization with TWIST1 KD." (PMID 39456533, 2024). "Since TGFβ1 and Twist1 initiate EMT at the top or bottom of the signaling cascade, respectively, these two models can be utilized simultaneously to study at which stage a given gene interferes with EMT, enriching our understanding of cancer metastasis mechanisms." (PMID 39648980, 2024). "Moreover, TWIST1 promotes EMT and enhances the motility of several cancer cells." (PMID 36900285, 2023). "The isolated cancer cells gain a mesenchymal feature with higher invasiveness by expressing transcription factors such as zinc finger protein SNAI1 (Snail), zinc finger protein SNAI2 (Slug), and twist-related protein 1 (TWIST1), which suppress epithelial biomarkers." (PMID 37047092, 2023). "Thus, inhibition of EMT-TFs, including TWIST1, to prevent cancer invasion during treatment can affect normal cell physiology." (PMID 38092725, 2023). "Thus, high Twist1 expression can promote EMT and lead to cancer cell metastasis." (PMID 36732432, 2023).
cancer (continued). "Hence, understanding the actions of pelitinib on Twist1 through Akt and MAPK signaling pathways may provide the basis for potential anti-cancer metastatic therapies and could help improve the survival rate of patients with HCC." (PMID 37495969, 2023). "In addition, small interfering RNAs against EMT transcription factors or key EMT-related genes have been used to inhibit cancer EMT, including Zinc-finger E-box-binding 1 (ZEB1), twist family bHLH transcription factor 1 (TWIST1), Nogo-B receptor and Wnt family member 1 (WNT1)." (PMID 36915713, 2023). "In addition, overexpression of EMT-TFs, e.g., Twist1, Zeb1, or Snai1, can also confer the stem cell traits to normal and transformed epithelial cells as well as cancer cells 19,53-55." (PMID 36276640, 2022). "In addition, we also analyzed the correlation between NUTF2 and the epithelial–mesenchymal transition (EMT) markers, Vimentin (VIM), TWIST1, Snail1 (SNAI1), Snail2 (SNAI2), Fibronectin 1 (FN1), and N‐cadherin (CDH2), which were widely accepted to be involved in cancer metastasis." (PMID 35155261, 2022). "Elevated expression of SLUG and TWIST1 significantly increased ALDH activity in PC3 cells, and this activity was significantly decreased by suppression of SOX2, indicating that SOX2 is a critical mediator of SLUG- and TWIST1-mediated cancer stem–like properties." (PMID 34809669, 2021). "Based upon the evidence that a fraction of TWIST1+ stromal cells harbor the same chromosomal changes of epithelial cancer cells, we could now re-interpret those findings and trisomic fibroblasts as being indeed EMT cancer cells in the peritumoral stroma." (PMID 34768901, 2021). "During metastasis, cancer cells of epithelial origin often reprogram their cells to a mesenchymal type, in a process termed epithelial–mesenchymal transition (EMT) that helps to spread them to other organs, via transcriptional programming, which is regulated by TWIST1, ZEB1, SLUG, and SNAIL." (PMID 33917757, 2021). "Since Twist1 is also enriched at diverse distant sites with respect to the TSS, this suggests a hitherto undiscovered role of Twist1 in the regulation of long-distance chromatin interactions that further impinge on chromosomal and genomic stability in cancer cells." (PMID 32337580, 2020). "It should be underlined that several various signaling pathways (i.e., MAPK, PI3K/Akt signaling pathways), transcription factors (i.e.,TWIST1, Snail, Slug, ZEB1/2), and cytokines (i.e., VEGF, TGFβ) may be involved in the migration and invasiveness of cancer cells." (PMID 32260268, 2020). "However, the correlation between TWIST1 with CIN and DSB genes is cancer subtype-specific." (PMID 32337580, 2020). "However, it is not known how MYC and TWIST1 work together to promote the metastasis of cancer cells." (PMID 31933479, 2020). "Therefore, LUADT1 may sponge miR-15a-3p to upregulate Twist1 in SCLC, thereby promoting cancer cell invasion and migration." (PMID 31842825, 2019). "It has been evident that thymoquinone treatment inhibits TWIST1 promoter activity and decreases its expression in breast cancer cell lines; leading to the inhibition of epithelial-mesenchymal transition (EMT) mediated cancer cell migration, invasion and metastasis." (PMID 28881699, 2017). "Transient activation of Twist1 promotes cancer stemness, even when EMT has not been induced." (PMID 28649800, 2017). "(2012) also indicated that turning off Twist1 reversed the EMT process, leading to the subsequent occurrence of MET for colonization and the formation of metastases, indicating that Twist1 is an important regulator of epithelial plasticity during cancer metastasis." (PMID 28649800, 2017). "While Twist1 methylation may be a useful biomarker to predict the clinical outcomes as to recurrence and survival in patients with cancers, it remains controversial whether or not the Twist1 methylation at the promoter region leads to silencing of the gene." (PMID 26695186, 2015).
cancer (continued). "TWIST1 has been indicated as oncoprotein, which, with the support of other transcription factors, like SNAIL1, SLUG and ZEB1, regulates the expression of Cadherins and some other proteins involved in both of EMT and metastasis process, as well as cancer initiation and progression." (PMID 26023736, 2015). "In line with this view, immunohistochemical analysis of TWIST1 in human non-invasive breast cancers (ductal carcinomas in situ, DCIS) has revealed frequent overexpression of this EMT inducer within the bulk of the primary lesion, while the cancer cells maintain an epithelial phenotype." (PMID 22654675, 2012). "This reveals a previously unknown characteristic of EMT in cancer not induced via TWIST1." (PMID 39851508, 2025). "Interestingly, the RING‐finger E3 ligase RNF8 promotes the K63‐linked ubiquitination of Twist1 at K38, which enhances, but not decreases, the protein stability of Twist1, leading to its nuclear localization thereby playing critical roles in cancer drug resistance." (PMID 35601657, 2022). "Thus, an increase in the methylated TWIST1 level in blood may suggest the presence of some kind of cancer, not just that limited to colorectal neoplasia." (PMID 29682198, 2018). "Thus, it remains uncertain whether or not epigenetic changes are related to Twist1 activation in cancer cells." (PMID 26695186, 2015). "However, the functional domains of TWIST1 have not been thoroughly studied and many questions are unanswered regarding their potential interacting partners, which in turn can be highly valuable for understanding the mechanism of cancer cell dissemination." (PMID 22891766, 2012). "High mRNA levels of RKIP correlated negatively with those of SNAIL1, SNAIL2, TWIST1, TWIST2, ZEB1, and ZEB2 in several but not all carcinomas." (PMID 39335152, 2024). "In this review, we highlight non-metastatic roles for TWIST1 and related EMT factors in cancer and other disorders, discuss recent findings in the areas of therapeutic resistance and stemness in cancer, and comment on the potential to target EMT for therapy." (PMID 38139368, 2023). "Expression of TWIST1 and ZEB2 was largely absent in cancer cells, and, in 6 of the 8 cancer types, even the 95th percentile of Vimentin expression levels in cancer cells was lower than its average expression level in CAFs." (PMID 33972543, 2021). "Cancer cell-intrinsic properties like proliferation, apoptosis or invasiveness were not different between the non-metastatic MYC-HCC and the metastatic MYC/Twist1-HCC." (PMID 31933479, 2020). "Taken together, this evidence suggests that it is the target genes down-stream of Twist1 (for example: CD24), rather than EMT, that confers cancer stem cell properties." (PMID 28099910, 2017). "Not all of the cancer cell lines expressed the same STAT3 downstream targets but cyclin D1, Bcl-2, survivin, DNMT1 and TWIST1 were among the most common STAT3 downstream targets expressed and were inhibited by the STAT3 inhibitor, FLLL32." (PMID 20712901, 2010). "Distinct from carcinoma EMT, TWIST1 did not generate an E- to N-cadherin "switch" in GBM cell lines." (PMID 20646316, 2010). "As both cancer and non-cancer cells with EMT exhibit increased migratory capacities, elevated oxidative flexibility may be a commonly conferred characteristic, regardless of TWIST1 expression." (PMID 39851508, 2025). "At the concentrations tested, harmine did not affect the viability of cells significantly, suggesting that its inhibition of cancer cell migration and invasion is largely independent of its cytotoxicity, but due to its ability to affect regulators of EMT such as Twist1." (PMID 33626096, 2021). "Importantly, several studies have demonstrated that overexpression of the Bcl-2 family proteins is not always sufficient to induce pro-invasive properties of cancer cells, and could require the co-expression of other proteins stimulating invasiveness, such as c-Myc, N-Myc, or Twist1." (PMID 31921862, 2019).
infection (11 papers, 2016 to 2025). The state of being infected such as from the introduction of a foreign agent such as serum, vaccine, antigenic substance or organism. "As there were more macrophages at the infection site, we speculated that TWIST1 might be associated with the migration and recruitment of macrophages to the infection sites in marrow." (PMID 32595631, 2020). "All these data indicate that the up-regulated expression of TWIST1 might be associated with macrophages accumulation at infection site." (PMID 32595631, 2020). "We established stable 4T1 cell lines expressing Twist1 shRNA via lentiviral infection and puromycin selection." (PMID 40963917, 2025). "After infection and puromycin selection, cellular proteins were extracted to detect the expression of Twist1 in 3T3-L1 and C3H10T1/2 cells." (PMID 37996425, 2023). "Results showed a much higher amount of TWIST1-positive staining around the infection site than that in the control group." (PMID 32595631, 2020). "In human chondrocytes, TET1 and TET3 mRNA level were increased by Ad-TWIST1 infection by approximately 2 fold." (PMID 28220902, 2017). "As macrophages and neutrophils are the main phagocytes to defend S. aureus infection in early infection stage, we speculate that S. aureus infection may stimulate cells migration by up-regulating the expression of TWIST1." (PMID 32595631, 2020). "The mRNA level and protein level of TWIST1 decreased gradually with the severity of infection." (PMID 32595631, 2020). "As macrophages were recruited around the infection site and TWIST1 was highly expressed around the infection, we speculated that the expression of TWIST1 might be up-regulated in macrophages around infection." (PMID 32595631, 2020). "In TC28 cells, MMP3 mRNA level was also increased by Ad-TWIST1 infection by approximately 3 times." (PMID 28220902, 2017). "To validate the role of TWIST1 expression in the miR-151-3p regulation of cell migration, we transfected MDA-MB-231 cells with the TWIST1 cDNA plasmid to overexpress the protein coding region (that lacks the TWIST1 3’UTR) after infection with adenoviruses expressing miR-151." (PMID 27930738, 2016). "Our data reveal that S. aureus infection may stimulate the expression of TWIST1 which up-regulates the expression of MMP9 and MMP 13, thereby promoting the migration of macrophages toward the infection sites for scavenging S. aureus." (PMID 32595631, 2020). "We checked MMP3 promoter methylation status by bisulfite sequencing analysis, but the percentage of non-methylated CpG sites did not change after Ad-TWIST1 infection." (PMID 28220902, 2017).
adenocarcinoma (8 papers, 2007 to 2024). A common cancer characterized by the presence of malignant glandular cells. "Five remaining loci, CDH13, CDX2, OPCML, SFRP1 and TWIST1 were designated as “late” loci; significantly elevated DNA hypermethylation was only detected in adenocarcinoma, as compared with AIS." (PMID 21731750, 2011). "Twist1 co-expression with KrasG12D in the lung also appeared to promote transformation of the predominantly benign lung adenoma tumor phenotype of CR mice to a malignant phenotype composed mostly of adenocarcinomas as determined by a veterinarian pathologist (p<0.0001 Fisher's exact test)." (PMID 22654667, 2012). "The physical binding of NKX3-1 to the TWIST1 promoter might block the mesenchymal drive of TWIST1, until NKX3-1 expression is down-regulated or lost in PIN or adenocarcinoma lesions." (PMID 23368843, 2013).
hematological malignancies (8 papers, 2015 to 2025). "TWIST1, a key EMT transcription factor, participates actively in the progression of various hematological malignancies." (PMID 39941895, 2025).
kidney disease (5 papers, 2016 to 2025). "The role of Twist1 has been extensively studied in the kidney and is implicated in kidney disease." (PMID 41332587, 2025). "The role of activated Twist1 in renal disease remains unclear, although recent studies have linked Twist1 with renal fibrogenesis." (PMID 35182235, 2022). "A previous study showed that HIF-1α, Snail, and other upstream signal molecules induced by injury regulate Twist1 transcriptional activation in renal disease." (PMID 35182235, 2022). "We find that Twist1 was upregulated in the damaged glomerulus in human kidney disease and murine models and that Twist1 in the murine podocyte limited CCL2-dependent macrophage accumulation, podocyte loss, and albuminuria." (PMID 34369383, 2021). "In the current study, we examined the role of Twist1 in proteinuric kidney disease." (PMID 34369383, 2021). "The transcription factor Twist1 regulates several processes that could impact kidney disease progression, including epithelial cell differentiation and inflammatory cytokine induction." (PMID 34369383, 2021).
gastrointestinal tumors (3 papers, 2010 to 2025). "Of the top 10 genes that were hypermethylated in CIMP-H compared to CIMP-L tumors, 5 have previously been implicated in the pathogenesis of gastrointestinal tumors (NTRK3, HS3ST2, TWIST1, CD40 and EYA4)." (PMID 20492682, 2010). "Additionally, research can explore whether ISL suppresses the progression of digestive system tumors through m6A/IGF2BP3-mediated stabilization of TWIST1 mRNA, and so on." (PMID 40978472, 2025).
metabolic disease (3 papers, 2020 to 2023). A congenital disorder (due to inherited enzyme abnormality) or acquired (due to failure of a metabolically important organ) disorder resulting from an abnormal metabolic process. "Nevertheless, the roles of Twist1 in skeletal muscle remain obscure as the expression level of Twist1 in skeletal muscle was unaltered in the patients with metabolic disorders." (PMID 37784111, 2023).
cardiovascular diseases (2 papers, 2021 to 2024). "It is reported that PGC1α activates angiogenic signaling and mediates aging-related cardiovascular diseases and that inhibition of Twist1 activity in fat cells increases the activity of PGC1α." (PMID 33764901, 2021).
genetic diseases (2 papers, 2020 to 2021). "In humans, TWIST1 mutation leads to Saethre‐Chotzen syndrome, a genetic disorder characterized by the premature fusion of certain skull bones." (PMID 33470057, 2021). "One of the transcription factors we identified is TWIST1, which has not been extensively studied in human muscle biology and relevant genetic diseases." (PMID 32011235, 2020). "However, TWIST1 expression in human myogenic development and its relevance to genetic diseases has not been studied until now." (PMID 32011235, 2020).
epithelial neoplasm (1 paper, 2012). A benign or malignant neoplasm that arises from and is composed of epithelial cells. "It has been reported that, distinct from EMT in epithelial neoplasms, TWIST1 did not generate a "cadherin switch"." (PMID 23029385, 2012).
head and neck tumors (1 paper, 2020). "Not all E2-positive head and neck tumors have downregulation of TWIST1 compared with E2-negative tumors as evidenced by TCGA data, but there is a significant trend for downregulation." (PMID 33298572, 2020).
heart disease (1 paper, 2025). "Evidently, Twist1 mediates the occurrence of heart disease and the progression of cardiac fibrosis, plays an important role in heart disease, and is a promising target for the treatment of HF." (PMID 40283937, 2025).
hematopoietic cancers (1 paper, 2021). "Although there are indications of a probable association between Twist1 and IL-17 in hematopoietic cancers, this association was poorly evidenced in tumors from epithelial cells." (PMID 34830027, 2021).